KIR2DL1 (killer cell immunoglobulin like receptor, two Ig domains and long cytoplasmic tail 1)
Description:
Receptor on natural killer (NK) cells for some HLA-C alleles such as w4 and w6. Inhibits the activity of NK cells thus preventing cell lysis.
Synonyms: NKAT-1; CD158a; NKAT1; cl-42; 47.11; p58.1; KIR-K64; KIR221; NKAT
Tractability: Antibody: a drug acting on it is in phase 2 or 3 trials; UniProt places it where antibodies can reach, with high confidence; its Gene Ontology location is reachable by antibodies, with high confidence; UniProt predicts a signal peptide or a membrane-spanning region.
Target class: Membrane receptor
Gene: Protein-coding gene on chromosome 19 (54,769,793 to 54,784,332, forward strand). Ensembl gene ENSG00000125498.
Subcellular location: Cell membrane
Pathways (Reactome):
Immune System: Immunoregulatory interactions between a Lymphoid and a non-Lymphoid cell
Gene Ontology:
Molecular function: protein binding; immune receptor activity; signaling receptor activity; transmembrane signaling receptor activity
Biological process: natural killer cell inhibitory signaling pathway; immune response; immune response-inhibiting cell surface receptor signaling pathway
Cellular component: plasma membrane
Genetic constraint (gnomAD): Loss-of-function variants: 38 observed, 30.43 expected, observed/expected ratio (o/e) 1.25, 90% interval 0.96 to 1.63. The synonymous counts are far from expectation, so gnomAD's model fits this gene poorly and the ratio says little. Missense variants: 531 observed, 351.43 expected, observed/expected ratio (o/e) 1.51, 90% interval 1.41 to 1.62. Synonymous variants: 179 observed, 135.27 expected, observed/expected ratio (o/e) 1.32, 90% interval 1.17 to 1.5.
Homologues: Orthologues: mouse Kir3dl1 (31% identical), rat Kir3dl1 (31% identical), mouse Kir3dl2 (30% identical), tropical clawed frog xilr1 (16% identical). Paralogues in human: KIR2DL3 (90% identical), KIR3DL1 (84% identical), KIR3DL2 (83% identical), KIR3DL3 (71% identical), KIR2DL4 (46% identical), KIR2DS4 (44% identical), LILRB1 (35% identical), LILRB2 (34% identical), LILRB3 (34% identical), LILRB5 (31% identical), LILRA6 (28% identical), LILRA2 (28% identical), and 13 more.
Diseases named in the same sentence as KIR2DL1 in open-access papers:
KIR2DL1 is named in the same sentence as 74 diseases in open-access papers, as found by Europe PMC text mining. Sharing a sentence is not in itself a finding about the gene and the disease. The quoted sentences say what the papers report.
COVID-19 (15 papers, 2021 to 2025). A disease caused by infection with severe acute respiratory syndrome coronavirus 2. "Regarding KIR gene polymorphisms, the combination of the activating receptor KIR2DS2 with the HLA-C1 allele has been associated with reduced mortality in COVID-19 patients, whereas increased expression of the inhibitory receptor KIR2DL1 has been observed in individuals with severe disease." (PMID 40650195, 2025). "Our results demonstrate an overexpression of the functional markers IFN-γ and Granzyme B, as well as the inhibitory receptor KIR2DL1, on peripheral blood NK cells from severe COVID-19 patients, compared to uninfected controls." (PMID 40927375, 2025). "Genetic analysis in a Sardinian population revealed a prevalence of inhibitory KIR receptors like KIR2DL1 and KIR2DL3 in COVID-19 patients, indicating increased susceptibility in individuals with such genetic profiles." (PMID 40244151, 2025). "Nonetheless, the reduced KIR3DL1/Bw4 pairs in severe patients and increased KIR2DL1/C2 pairs in mild patients indicate that the potency of NK cell education influences COVID-19 vulnerability." (PMID 36849422, 2023). "Prior to performing NK cell cytotoxicity assays, we confirmed the expression of NKG2A and KIR2DL1 on the NK cells derived from COVID-19 positive patients utilized for these assays by flow cytometry." (PMID 37483595, 2023). "There was a significant enhancement of COVID-19 positive patient derived NK cell killing of SARS-CoV-2 infected Caco-2 cells with the addition of either NKG2A or KIR2DL1 blockade (p<0.05)." (PMID 37483595, 2023). "We demonstrated the possible therapeutic use of anti-NKG2A and/or anti-KIR2DL1 to restore NK function in COVID-19 patients." (PMID 37483595, 2023). "The KIR2DL1/HLA-C2 complex has been linked to increased disease severity, and the frequency of KIR2DS4 and KIR3DL1 genes has been associated with a risk of severe COVID-19, suggesting a significant role of these genetic markers in antiviral immunity." (PMID 40244151, 2025). "Furthermore, NK cells from COVID-19 patients over-express inhibitory KIR2DL1 or KIR2DL2/DL3 receptors, which specifically recognize HLA-C molecules, compared to healthy donors." (PMID 37342247, 2023). "Clustering analysis identified unique COVID-19 positive clusters to be NKG2A+KIR2DL1+NKG2C-." (PMID 37483595, 2023). "Utilizing blocking antibodies specific for receptors NKG2A and KIR2DL1, we found that both NKG2A and KIR2DL1 blockade markedly enhances the ability of NK cells from COVID-19 positive patients to lyse SARS-Cov-2 infected cells." (PMID 37483595, 2023). "In addition to functional markers, we evaluated the expression of KIR2DL1, an inhibitory receptor belonging to the KIR family, and found it overexpressed on NK cells from patients with severe COVID-19." (PMID 40927375, 2025). "In particular, a strong interaction of KIR2DL1 and HLA-C2 ligands seems to promote the large and stable expansion of adaptive NK cells in human CMV infection, as observed in this study of COVID-19 patients with fatal outcomes." (PMID 37342247, 2023). "Moreover, in patients with severe COVID-19, NKG2C expression was negatively correlated with NKp30 (p=0.0085, r=-0.6250) and positively correlated with KIR2DL1 (p=0.0024, r=0.6990)." (PMID 37342247, 2023). "Among KIR/HLA-C pairs, inhibitory KIR2DL1 binds to C2 with higher affinity than KIR2DL2/3 to C1, which may account for the increased KIR2DL1 + C2 combination in mild, but not severe COVID-19 patients." (PMID 36849422, 2023). "Finally, we also assessed the ability of NKG2A and KIR2DL1 blockade to enhance the cytotoxic activity of NK cells from patients who were COVID-19 negative against spike expressing infected CACO-2 cells." (PMID 37483595, 2023).
COVID-19 (continued). "After establishing that NK cells exhibit enhanced cytotoxicity against SARS-CoV-2 infected Caco-2 cells as opposed to non-infected cells, we assessed if blockade of NKG2A, KIR2DL1 or a combination can enhance the NK cell-mediated cytotoxicity using blocking antibodies (n=3 COVID-19 positive donors)." (PMID 37483595, 2023). "KIR2DL1, KIR2DL3, KIR3DL1 and KIR3DL2 are inhibitory NK cell receptors and enhanced interactions via these receptors on CD8+ T cells could indicate a more balanced functional regulation of CD8+ T cells in mild COVID-19." (PMID 36591270, 2022). "COVID-19 negative enriched clusters (C10 and C11) are characterized by low NKG2A, high NKG2C and variable KIR2DL1 expression." (PMID 37483595, 2023). "In contrast to testing NK cells from patients with COVID-19, these NK cells did not exhibit a statistically significant increase in killing with NKG2A blockade but did exhibit increased killing with KIR2DL1 blockade." (PMID 37483595, 2023). "An increased frequency of KIR2DL1+HLA-C2+ combination, particularly without the activating counterpart KIR2DS1 or KIR2DS5 in mild COVID-19 cases than severe COVID-19 cases, suggests a protective role for KIR2DL1+HLA-C2+ against developing severe COVID-19." (PMID 35273641, 2022).
leukemia (8 papers, 2012 to 2024). A malignant (clonal) hematologic disorder, involving hematopoietic stem cells and characterized by the presence of primitive or atypical myeloid or lymphoid cells in the bone marrow and the blood. "That is, the high frequency of inhibitory KIR2DL1, KIR2DL2 and KIR3DL1 strongly suppresses NK cell function, thus increasing the risk of developing leukaemia." (PMID 38527290, 2024). "Among children with leukemia undergoing haploidentical transplants, donor-derived KIR2DL2/3+ NK cells showed reduced alloreactivity against HLA-C2 leukemia cells, while KIR2DL1+ NK cells had robust killing against HLA-C1 leukemia cells." (PMID 36613644, 2022). "We focused on Allo C2, since KIR2DL1 displays a more stringent recognition of HLA-C allotypes, and a greater number of HLA-C1/C1 than HLA-C2/C2 leukemia blasts, in addition to the pediatric leukemia cell line NALM-16 (HLA-C1 hemizygous) were available." (PMID 32764469, 2020). "KIR phenotypes analysis in Belgian leukemia patients indicated significantly higher frequencies of inhibitory KIR2DL1, KIR2DL2, and KIR2DL3 genes, suggesting their contribution for the lack of antitumor responses of NK cells." (PMID 27708784, 2016). "However, further investigations are needed to evaluate the role of other inhibitory KIR receptors, such as KIR2DL1, KIR3DL1 and KIR3DL2, in anti-leukemia NK cell responses, particularly against AML." (PMID 32708751, 2020). "Additionally, the results highlighted a negative correlation between the pathogenesis of leukemia and KIR3DL1, KIR3DS1, KIR2DL1, and KIR2DL5 genes, a very suggestive finding that KIR polymorphisms are associated with susceptibility to leukemia in Hans." (PMID 27708784, 2016).
endometriosis (7 papers, 2020 to 2025). The growth of functional endometrial tissue in anatomic sites outside the uterine body. "Stage III/IV endometriosis exhibits significantly greater KIR2DL1+ NK levels than stage I/II samples." (PMID 36613776, 2022). "Levels of ITIM-KIRs, KIR2DL1, and intracellular adhesion molecule-1 (I-CAM) are upregulated on pNK cells of patients with endometriosis, causing inhibition in pNK cell cytotoxicity." (PMID 35628346, 2022). "The inhibitory receptor KIR2DL1 is upregulated on both peripheral blood and peritoneal NK cells in endometriosis patients." (PMID 35628346, 2022). "On the other hand, due to the upregulated expression of the inhibitory receptors observed in endometriosis, the inhibition of KIR2DL1, LILRB1/2, and NKG2A by monoclonal antibodies may have therapeutic effects on endometriosis." (PMID 36865552, 2023). "Aberrant expression of KIR2DL1 impaired NK cell cytotoxicity in endometriosis." (PMID 37662927, 2023). "Similarly to CD158a+, endometriosis KIR2DL1 + NK cell levels were significantly higher than those of the control groups (17.4% ± 8.4% vs. 11.7% ± 5.5%, p = 0.011)." (PMID 36613776, 2022). "Blocking the interaction between KIR2DL1 and its ligand could be a possible treatment in endometriosis but should be examined further on endometriosis cells and lesions before conclusions can be drawn." (PMID 35628346, 2022). "We found that, except for FGB, KIR2DL1, and KIR2DL3, all other hub genes showed significantly different expression levels in the endometriosis and normal control groups." (PMID 37662927, 2023). "Endometriosis pathogenesis seems to be marked by the overexpression of NK inhibitor receptors (KIRS), namely, CD158a+, KIR2DL1, CD94/NKG2A, PD-1, NKB1, and EB6, and inhibiting ligands such as PD-L1, HLA-E, HLA-G, and HLA-I." (PMID 36613776, 2022). "The observed increase in the proportion of CD158a+ (KIR2DL1) NK cells in the peripheral blood and peritoneal fluid in endometriosis patients suggested reduced NK cell cytotoxicity in endometriosis." (PMID 32184413, 2020). "As per their results, endometriosis pathogenesis is marked by the overexpression of NK inhibitor receptors (KIRS), namely, CD158a+, KIR2DL1, CD94/NKG2A, PD-1, NKB1, and EB6, and inhibiting ligands such as PD-L1, HLA-E, HLA-G, and HLA-I in ectopic endometrial lesions." (PMID 36613776, 2022).
viral infection (7 papers, 2015 to 2025). "Possibly, the high-avidity of KIR2DL1 alleles expressed by “clonal” NKG2C+ subset impairs the overall control of the viral infection or of these consequences." (PMID 37342247, 2023). "Certain KIR receptors, like KIR2DL1 and KIR2DS1, recognize HLA-C molecules, which can influence NK cell activation or inhibition and, consequently, the immune response to viral infections." (PMID 39599823, 2024). "On the contrary, the presence of C2 alleles (HLA-CLys80) such as HLA-C*07:01 and -C*06:02, which are ligands for the inhibitory KIR2DL1 and activating KIR2DS1, would theoretically lead to lower NK inhibition and higher activation would be more beneficial for the clearance of viral infections." (PMID 35960731, 2022). "The presumed mechanism underlying this observation is that the weaker inhibitory interaction of KIR2DL3 with C1, but not the stronger inhibitory interaction of KIR2DL2 and KIR2DL1 with C1 and C2, could allow penetrance of activating signals during viral infection." (PMID 29664957, 2018).
HCMV infection (4 papers, 2013 to 2022). "Arrb2 mediates the binding of Src homology-containing tyrosine phosphatases to KIR2DL1 to regulate the inhibitory signaling of NK cells, and Arrb2-deficient mice were less susceptible to cytomegalovirus infection compared with wild-type mice." (PMID 28525390, 2017). "Altogether, our data indicate that HCMV infection induces major changes in dNK cell receptor repertoire with increases in NKp44, NKG2C and decreases in NKp46, KIR2DL1, KIR2DL4 and ILT2 expression." (PMID 23592985, 2013).
malaria (4 papers, 2012 to 2025). Malaria is a serious and sometimes fatal disease caused by a parasite that commonly infects a certain type of mosquito which feeds on humans. "Of these, only V111, which is found within the RIFIN-binding hydrophobic pocket of KIR2DL1, is reported to be common in malaria-endemic regions, with V111F found in Baka populations in northern Gabon/southwest Cameroon24." (PMID 40500441, 2025). "We were not able to directly compare malaria outcomes in HLA-C*06:02+ individuals with and without KIR2DL1, however, as KIR2DL1 was present in 99% of individuals in our cohort." (PMID 33815410, 2021). "Additionally, while it would have been interesting to explore the influence of HLA-KIR ligand pairs (i.e. KIR2DL1/HLA-C*06:02 and KIR3DL1/HLA-B*53:01) on malaria outcomes, the prevalence of both of these inhibitory KIR in our cohort was >98%." (PMID 33815410, 2021).
preeclampsia (4 papers, 2015 to 2020). Preeclampsia is a hypertensive disorder of pregnancy that is characterized by new-onset hypertension with proteinuria presenting after 20 weeks of gestation, and depending on mild or severe forms may initially present with severe headache, visual disturbances, and hyperreflexia. "Clinical consequences of KIR allelic polymorphism on KIR diseases were identified for a few KIR genes such as KIR2DL1 for preeclampsia, and KIR2DL1, KIR3DL1 for HSCT outcome." (PMID 33271841, 2020). "Because inhibitory C2‐specific KIR2DL1 correlates with preeclampsia, whereas activating C2‐specific KIR2DS1 protects, this association pointed to KIR2DS5*006 being an activating C2‐specific receptor." (PMID 28685972, 2017). "Thus the emergence of 2DL1*022 and 2DL1*026, as well as the general increase of weaker inhibitory KIR2DL1 allotypes, in the KhoeSan could have acted to reduce the incidence of preeclampsia." (PMID 26292085, 2015).
pregnancy disorder (4 papers, 2015 to 2021). A disorder that is related to pregnancy. "Because interaction of KIR2DL1 with C2 is associated with risk of pregnancy disorder, these functional changes are potentially advantageous." (PMID 26292085, 2015). "Interaction between KIR2DL1 with HLA-C2 is associated with the risk of pregnancy disorder, whereas KIR2DS1 protects from pregnancy disorders via interacting with HLA-C2." (PMID 34054831, 2021). "KIR2DL1 is also critical to our model of pregnancy disorders, as it is strongly inhibitory for HLA-C allotypes bearing C2 epitopes." (PMID 27815424, 2016).
acute myeloid leukemia (3 papers, 2011 to 2025). Acute myeloid leukemia (AML) is a group of neoplasms arising from precursor cells committed to the myeloid cell-line differentiation. "Phase 1 studies of IPH2101, a human IgG4 mAb against KIR2DL1, KIR2DL-2 and KIR2DL-3, illustrated that blocking KIRs with IPH2101 enhances NK cell cytotoxicity against acute myeloid leukemia (AML) and multiple myeloma (MM) without eliciting autoimmune response." (PMID 35008589, 2021).
influenza (3 papers, 2012 to 2021). An acute viral infection of the respiratory tract, occurring in isolated cases, in epidemics, or in pandemics; it is caused by serologically different strains of viruses (influenzaviruses) designated A, B, and C, has a 3-day incubation period, and usually lasts for 3 to 10 days. "NK cell response related genes such as CD247, KIR2DL4, KIR3DL1, KIR3DL3 and KLRB1 were down-regulated only in moderate and severe patients while genes such as KIR2DL1, KIR2DS4 and KIR3DL2 were down-regulated in all three groups of influenza patients." (PMID 25365328, 2014).
lymph node metastasis (3 papers, 2022 to 2023). "The results showed that alcohol consumption, degree of differentiation, depth of infiltration, lymph node metastasis, clinical stage, and Fn + CD8+KIR2DL1 positive group were independent risk factors affecting the prognosis of ESCC (p < .05)." (PMID 34935568, 2022). "The results showed that gender, smoking, alcohol consumption, degree of differentiation, depth of invasion, lymph node metastasis, clinical stage, and Fn + CD8+KIR2DL1 positive group were correlated with overall survival (p < .05)." (PMID 34935568, 2022).
chronic hepatitis C (2 papers, 2017 to 2018). "We observed a significant association with chronic hepatitis C susceptibility for HLA-Bw4 (P = 0.00012; odds ratio [OR] = 1.66) and significant protective associations for HLA-C2 and KIR2DL1-HLA-C2 (both P = 0.00099; OR = 0.57)." (PMID 29731972, 2018). "The frequency of the KIR2DL1-HLA-C2 combination in patients with chronic hepatitis C was significantly lower than that in controls (13.1% versus 20.9%; P = 0.00099; OR = 0.57)." (PMID 29731972, 2018). "While, we were unable to KIR genotype the present patient cohort, to allow us to precisely examine KIR2DL2 expression, we did observe maintenance of KIR2DL3 expression and down-regulation of KIR2DL1 and KIR3DL1 in chronic hepatitis C compared to healthy controls." (PMID 28533779, 2017).
Crohn disease (2 papers, 2014 to 2023). A gastrointestinal disorder characterized by chronic inflammation involving all layers of the intestinal wall, noncaseating granulomas affecting the intestinal wall and regional lymph nodes, and transmural fibrosis. "As in ulcerative colitis, human data studies show a negative influence of KIR2DL2/KIR2DL3 in Crohn's disease development and a protective effect for the KIR2DL1/HLA-C2 interaction." (PMID 25310588, 2014).
Diabetes (2 papers, 2013 to 2025). "Conversely those homozygous for HLA-C2 lack ligand for KIR2DL1 and are associated with KIR2DS2 and diabetes." (PMID 23957956, 2013).
glioblastoma (2 papers, 2022). The most malignant astrocytic tumor (WHO grade IV). "In the present study, we aimed to analyze the frequency, phenotype, and function of KIR2DL-1,-2/3 expressing NK-cells in glioblastoma patients and to evaluate whether targeting of KIR2DL-1,-2/3 augments the cytolytic activity of tumor-derived NK-cells." (PMID 35474089, 2022). "Peripheral blood and freshly prepared tumor cell suspensions (n = 60) as well as control samples (n = 32) were investigated for the distribution, phenotype, and functional relevance of CD158ab/KIR2DL1,-2/3 expressing NK-cells in glioblastoma (GBM) patients." (PMID 35474089, 2022). "Blockade with a specific KIR2DL-1,2/3 mAb reversed NK-cell inhibition and significantly enhanced degranulation and IFN-γ production of IL-2-preactivated NK-cells in the presence of primary glioblastoma (GBM) cells." (PMID 36601109, 2022).
glioma (2 papers, 2022 to 2023). A benign or malignant brain and spinal cord tumor that arises from glial cells (astrocytes, oligodendrocytes, ependymal cells). "To confirm the KIR2DL1 expression patterns, we obtained the RNA sequencing data of gliomas from the GlioVis data portal and The Cancer Genome Atlas (TCGA) database." (PMID 37762486, 2023).